TNPO3 (transportin 3)
Diseases named in the same sentence as TNPO3 in open-access papers (continued):
Sharing a sentence is not in itself a finding about the gene and the disease.
clear cell renal cell carcinoma (4 papers, 2022 to 2025). "In clear cell renal cell carcinoma (ccRCC), a circRNA from the transportin 3 (TNPO3) gene, circ-TNPO3, directly binds to the IGF2BP2 protein, destabilizing SERPINH1 mRNA and inhibiting ccRCC cell proliferation." (PMID 39062595, 2024). "For instance, circ-TNPO3 bound to IGF2BP2, resulting in destabilization of SERPINH1 mRNA in clear cell renal cell carcinoma." (PMID 40883266, 2025).
limb-girdle muscular dystrophy (4 papers, 2013 to 2025). Limb-girdle muscular dystrophy (LGMD) is a heterogeneous group of muscular dystrophies characterized by proximal weakness affecting the pelvic and shoulder girdles. "Mutations in the TNPO3 gene (OMIM 608423) have been associated with a rare form of limb-girdle muscular dystrophy: LGMDD2 (previously LGMD1F) or LGMDD2 TNPO3-related." (PMID 41291251, 2025). "Limb-girdle muscular dystrophy (LGMD) D2 TNPO3-related is the subtype of dominant LGMDs caused by a mutation in the TNPO3 gene located on 7q32.1." (PMID 35309568, 2022). "Mutations in the TNPO3 gene result in a protein with an extended C-terminal domain, leading to the onset of LGMDD2, a rare form of limb girdle muscular dystrophy." (PMID 41291251, 2025). "Here, we report the identification of a frame-shift variant del A p.X924C at the TNPO3/Transportin-SR2 gene on chromosome 7q32.1 at position 128,597,310 (GRCh37/hg19) in all patients with limb girdle muscular dystrophy 1F." (PMID 23667635, 2013).
viral infection (4 papers, 2011 to 2022). "Nuclear pore protein Nup358 and the karyopherin TNPO3 have both been implicated as HIV cofactors whose depletion by short hairpin RNA (shRNA) reduces viral infection." (PMID 31851928, 2019). "TNPO3 encodes for transportin-3, which belongs to the importin beta family and transports into the nucleus serine/arginine-rich (SR) proteins, such as splicing factors, and HIV-1 proteins, thus contributing to viral infection." (PMID 35309568, 2022). "If TNPO3_mut cannot multimerize or interferes with regular multimerization of TNPO3_wt, this could explain the severe restriction of viral infection observed in LGMD1F cells despite the co-dominant expression of both TNPO3_wt and TNPO3_mut." (PMID 31465518, 2019).
ovarian carcinoma (3 papers, 2022 to 2025). A malignant neoplasm originating from the surface ovarian epithelium. "Note of worth, four genes (IPO9, KPNA2, TNPO3, and XPOT) and one gene (KPNA5) were consistently significantly up‐ and down‐regulated in ovarian cancer, respectively." (PMID 40145330, 2025). "However, another study reports that circ‐TNPO3 plays the oncogenic effects, thus contributing to PTX tolerance through the miR‐1299‐NEK2 axis in ovarian cancer." (PMID 35876041, 2022).
systemic lupus erythematosus (3 papers, 2013 to 2021). An autoimmune multi-organ disease typically associated with vasculopathy and autoantibody production. "Genes that were significant with at least two variables include: BTNL2 for alopecia areata, NOD2 for Crohn’s disease, PLA2R1 for membranous neuropathy, LMO1 for neuroblastoma, and TNPO3, UBE2L3, HLA-DRA, and HIC2 for systemic lupus erythematosus." (PMID 26170196, 2015). "GWAS identified genetic variants conferring the risks of autoimmune diseases systemic lupus erythematosus (SLE) and systemic sclerosis (SSc) at 7q32.1, harboring IRF5 and TNPO3 genes." (PMID 34208629, 2021).
muscle disorders (2 papers, 2022 to 2025). "The accurate diagnosis of LGMD D2 is made more easily with NGS techniques and by the introduction of TNPO3 in the panels of muscular disease-related genes." (PMID 35309568, 2022).
ulcerative colitis (2 papers, 2012 to 2013). An inflammatory bowel disease involving the mucosal surface of the large intestine and rectum. "Interestingly, rs4728142 is also associated with ulcerative colitis (UC) where both IRF5 and TNPO3 are reported as candidate genes." (PMID 22685416, 2012).
arachnodactyly (1 paper, 2022). "However, this individual case differs in some specific indicators of LGMDD2 (such as dysphagia, arachnodactyly, and dysarthria), and was associated with the heterozygous c.G2453A (R818P) mutation in exon 20 of TNPO3 (rs587777431)." (PMID 35646913, 2022).
Bethlem myopathy (1 paper, 2022). A usually autosomal dominant inherited movement disorder caused by mutations in the COL6A1, COL6A2, and COL6A3 genes. "Autosomal dominant LGMDs represent about 10–15% of LGMDs and include disorders due to defects of DNAJB6, transportin-3 (TNPO3), HNRNPDL, Calpain-3 (CAPN3), and Bethlem myopathy." (PMID 35309568, 2022).
colon adenocarcinoma (1 paper, 2021). "Consistent with electron microscopy data, we verified the critical role of TNPO3 on importing SRSF1 into nucleus of colon adenocarcinoma cells." (PMID 33602301, 2021).
colorectal cancer (1 paper, 2021). A primary or metastatic malignant neoplasm that affects the colon or rectum. "By association analysis, we were able to identify that the methylation levels of the CEP250, RAB21, and TNPO3 genes independently play crucial roles in colorectal cancer prognosis." (PMID 33670198, 2021).
congenital myopathies (1 paper, 2022). "Early involvement of the sartorius muscle has also been described in patients with mutations in SPEN1, RYR1, TNPO3, and MYH7, in some congenital myopathies like ACTA1, and in myofibrillar myopathies with mutations in DES or CRYAB." (PMID 35286480, 2022).
dilated cardiomyopathy (1 paper, 2023). Cardiomyopathy which is characterized by dilation and contractile dysfunction of the left and right ventricles. "The authors show that loss-of-interaction with the nuclear importer, TNPO3, causes cytoplasmic mislocalization of RBM20 variants linked to severe cases of dilated cardiomyopathy." (PMID 37463913, 2023).
lentivirus infection (1 paper, 2018). Virus diseases caused by the Lentivirus genus. "The CPSF6 binding interface is also conserved in HIV-2 and SIVmac, and we found that these viruses were particularly sensitive (more so than HIV-1) to TNPO3 depletion, further supporting the importance of this interaction for primate lentivirus infection." (PMID 30084827, 2018).
lymphopenia (1 paper, 2023). Reduction in the number of lymphocytes. "Collectively, these results suggest that the conditional ablation of Tnpo3 at the DN2/3 stage of thymocyte development leads to the total lack of iNKT cells, reductions of thymocyte numbers and peripheral T cell lymphopenia." (PMID 37339974, 2023).
myositis (1 paper, 2024). "Next, we colocalized IIM signals that overlapped IMD signals, and found seven potentially novel myositis associations mapped to immune-related genes, including BLK, IRF5/TNPO3, and ITK/HAVCR2, implicating a role for both B and T cells in IIM." (PMID 39044428, 2024).
infection (26 papers, 2010 to 2023). The state of being infected such as from the introduction of a foreign agent such as serum, vaccine, antigenic substance or organism. "TNPO3 has been described as a key factor in the infection by the human immunodeficiency virus (HIV-1), the causative agent of AIDS." (PMID 31465518, 2019). "Treatment of TNPO3 knock-down cells with 2 μM PF74 during infection strongly reduced the level of CPSF6 association with RTC/PIC to 18% (74 RTC/PIC analyzed)." (PMID 25517934, 2014). "Furthermore, we demonstrated that Daxx associates with incoming HIV-1 cores at 2 h post infection and resides within a complex containing CypA, TNPO3, TRIM5α, and its recently identified cofactor TRIM34." (PMID 32545337, 2020). "Relative to WT HIV-1, these viruses are also less sensitive to TNPO3 depletion which enables CPSF6 inhibition of infection." (PMID 37355754, 2023). "We found that TNPO3-deficient cells inhibited infection with four different IAV strains, whereas restoration of TNPO3 expression in knockout (KO) cells restored IAV infection." (PMID 35456945, 2022). "Depletion of both Nup358 and TNPO3 by shRNA reduced infection of K227I to a similar degree as wild-type virus." (PMID 31851928, 2019). "Our data confirm for the first time “in vitro” that adequate TNPO3 function is essential for HIV-1 replication infection, but they also provide insights into the role of TNPO3 in LGMD1F." (PMID 31465518, 2019). "Conversely, HIV-1N57S infection was inhibited by either TNPO3 or CPSF6 knockdown, only in HOS cells." (PMID 30084827, 2018). "The cellular proteins transportin 3 (TNPO3) and cyclophilin A (CypA) were shown to interact with the viral capsid and to affect infection by modulating uncoating." (PMID 26979152, 2016). "Interactions between IN and cellular cofactors LEDGF/p75 and TNPO3 were detected as early as 6 h post-infection." (PMID 23369367, 2013). "Immunoprecipitation experiments allowed us to detect interactions between IN and its cofactors LEDGF/p75 and TNPO3 at 6 h post-infection (p.i.)." (PMID 23369367, 2013). "Genetic and biochemical evidence suggests that the HIV-1 capsid is the viral determinant for the requirement of TNPO3 during infection." (PMID 23622145, 2013). "Resembling our observations with NUP153 knockdown cells, infection of TNPO3 depleted cells exhibited a similar profile of reduced sensitivity to PF74." (PMID 24130490, 2013). "TNPO3, transportin-SR2 or Tnp3, a member of the karyopherin β superfamily of proteins, is important for the ability of HIV-1 to achieve productive infection, as TNPO3 depletion leads to a reduction of HIV-1 infectivity." (PMID 22888429, 2012). "Intriguingly, simian immunodeficiency viruses (SIVs) exhibited the strongest dependency on TNPO3 for infection." (PMID 22888429, 2012). "By using HIV/MLV chimera viruses on the capsid protein, the Engelman Lab demonstrated that capsid is the genetic determinant for the requirement of TNPO3 during infection." (PMID 22888429, 2012). "Two genome-wide siRNA screens demonstrated the importance of TNPO3 for HIV-1 replication, and showed that TNPO3 acts early in infection, but after reverse transcription." (PMID 22145813, 2011). "As compared with the cells transfected with the control siRNA, infection of the TNPO3 depleted cells with the pNL4-3-GFP reporter virus was reduced 15-fold." (PMID 22145813, 2011). "This initial scan showed robust effects on infection efficiency for the nuclear import factors Transportin-3 and RanBP2, confirming observations from earlier studies; therefore, these genes were studied in detail as described in the following sections." (PMID 21423673, 2011). "The fate of the HIV-1 genome during the early phases of infection in the TNPO3-KD and rescue HeLa cells was examined next using quantitative PCR (qPCR)." (PMID 22145813, 2011). "The answer was surprising: infection by HIV-1 bearing the N74D substitution in CA was relatively resistant to depletion of TNPO3 in the target cell." (PMID 21994675, 2010).
infection (continued). "Similar to WT HIV-1, these viruses were impaired for infection of Nup35 and TNPO3 knockdown cells." (PMID 37355754, 2023). "However, integration was decreased more than 16-fold in PBMCs from LGMD1F patients in comparison to controls 5 days after infection suggesting an impairment of HIV-1 integration due to the TNPO3 defect leading to deep impact on viral replication." (PMID 31465518, 2019). "We show that TNPO3 facilitates infection in MEFs as in human cells." (PMID 24586169, 2014). "Consistent with our hypothesis, we observed that 87% of all RTC/PIC were positive for CPSF6 upon infection of the TNPO3 knock-down cell line (87 RTC/PIC analyzed)." (PMID 25517934, 2014). "Finally, we compared infection of HIV-1 and FIV attenuated GFP virus in HeLa cells stably transduced with either empty vector or vector encoding shRNA against NUP358 or TNPO3." (PMID 23902822, 2013). "It remains unclear whether the relatively weak in vitro interaction between HIV-1 CA and TNPO3 occurs within cells, and if it does, whether it is relevant for infection." (PMID 24103892, 2013). "As previously shown, depletion of NUP358 or TNPO3 inhibits infection of HIV-1." (PMID 23902822, 2013). "However, there is no genetic evidence pointing to integrase as the determinant for the requirement of TNPO3 during infection." (PMID 22888429, 2012). "In agreement with this idea, it has been proposed that TNPO3 plays a role in depleting capsid from the nucleus during infection, which may help PIC maturation in the nucleus." (PMID 22888429, 2012). "Similarly, by extensive mutagenesis of capsid, the Luban Lab demonstrated that capsid plays a major role in the requirement for TNPO3 during infection." (PMID 22888429, 2012). "It is tempting to speculate that the inability of FIV to be isomerized by NUP358Cyp may explain why it does not use NUP358 and associated transportin TNPO3 for nuclear entry and infection in human cells." (PMID 23902822, 2013). "To explore whether depletion of TNPO3 impact the occurrence of these processes, we performed infection of shRNA control and TNPO3 K.D. cells with HIV-1 in the presence of the integrase inhibitor raltegravir (RAL), and measure formation of 2-LTR circles and productive infection." (PMID 23622145, 2013). "However, compelling genetic and biochemical evidence has only been found for capsid, and thus it remains a question whether integrase is still a player in the ability of TNPO3 to assist HIV-1 replication once infection has taken place." (PMID 22888429, 2012). "As a positive control to inhibit infection of HIV-1 with wild-type (WT) CA, TNPO3 was also depleted using siRNA4." (PMID 37355754, 2023). "Meanwhile, type I interferon (IFN)-inducible miR-128 directly targets the TNPO3 mRNA, significantly downregulating TNPO3 mRNA and the subsequent protein expression levels, thus reducing HIV-1 replication and delays the spread of infection." (PMID 35456945, 2022). "To further understand the role of CPSF6 in the inhibition of HIV-1 observed in TNPO3-depleted cells, we measured the levels of 2-LTR circles during infection of TNPO3 K.D. cells." (PMID 23622145, 2013). "Curiously, although HIV-1 appears to rely upon NUP358, NUP153, TNPO3, and CPSF6 during infection, other lentiviruses only appear to share certain aspects of this mechanism." (PMID 24103892, 2013). "TNPO3 expression is required for proper nuclear localization of CPSF6; CPSF6 binding to CA cores too early during infection misregulates the upstream steps of uncoating and NPC engagement, blocking infection at the step of nuclear import." (PMID 24103892, 2013). "The HIV-1 requirements for TNPO3, NUP358, and NUP153 mapped to the nuclear steps of infection, either preceding or concomitant with integration." (PMID 24103892, 2013). "Effective transient TNPO3 depletion reduced wild type HIV-1 GFP R9 infection in HEK293 cells but did not rescue infection from MxB." (PMID 32553106, 2020).
infection (continued). "Furthermore, transportin-3 (TNPO3) and the nuclear pore complex component nucleoporin 153 (NUP153) were shown to be important for infection by HIV-1." (PMID 31652959, 2019). "The capsid of the primate lentivirus SIVmac does not interact with CypA or Nup358Cyp yet SIVmac shares with all lentiviruses the property of non-dividing cell infection and it interacts with other main early event factors such as TNPO3, CPSF6 and Nup153." (PMID 24586169, 2014). "Furthermore, capsid was found to be responsible for the viral requirement of various nuclear transport proteins, including transportin 3 and nucleoporins NUP153 and NUP358, during infection." (PMID 24103892, 2013). "Lee and coworkers also found that besides N74D, other CA mutants, including two previously shown to be impaired for infection of nondividing cells, were less dependent on TNPO3." (PMID 21994675, 2010). "TNPO3 is not required for infection by murine leukemia virus (MLV), a retrovirus that lacks the ability to infect nondividing cells and is thought to undergo a slow uncoating process." (PMID 21994675, 2010). "Intriguingly, infection of the HIV-1 capsid mutant N74D is independent of TNPO3." (PMID 22888429, 2012). "TNPO3, transportin-SR2 or Tnp3, a member of the karyopherin β superfamily of proteins, is important for the ability of human immunodeficiency virus (HIV-1) to achieve productive infection, as TNPO3 depletion in human cells leads to a dramatic reduction of infection." (PMID 22888429, 2012). "Similarly, TNPO3 depletion had no detectable effect on the amount of 2-LTR circles formed during infection with WT or CA mutant virus." (PMID 22145813, 2011). "As a control, we tested whether MLV integration, which requires cell division for infection and is not dependent on Transportin-3, showed altered integration targeting in the Transportin-3-depleted cells." (PMID 21423673, 2011). "While defects to integration were readily confirmed between the studies, the impact of TNPO3 knockdown on HIV-1 nuclear import is less certain; there has been little consensus between studies on whether 2-LTR circle levels drop or remain unchanged during infection." (PMID 24103892, 2013). "Therefore, relative to control cells, cells that express the N-terminal FG repeat-containing portion of Nup358 supported undiminished infection by primate lentiviruses whether or not their capsids bind cyclophilins (89G versus 89V, SIVmac) or TNPO3 (74N versus 74D)." (PMID 24586169, 2014). "These control experiments revealed that simultaneous depletion of TNPO3 and CPSF6 does not affect HIV-1-N74D infection." (PMID 23622145, 2013). "Overall, in the case of lentiviruses, a correlation exists between TNPO3 binding to integrase and the requirement of TNPO3 in infection The fact that the integrase of FIV interacts with TNPO3 and that TNPO3 is not required for FIV infection suggests the existence of two distinct groups of viruses." (PMID 22888429, 2012).
cancer (3 papers, 2013 to 2025). A tumor composed of atypical neoplastic, often pleomorphic cells that invade other tissues. "The genes BLK, FAM167A, STAT1, STAT4, TNPO3, and TNIP1 are associated with AIDs, and CDC37, DDX6, MAPT, STAT1, STAT4, and UBE3A are associated with cancers." (PMID 40429780, 2025).
myopathies (2 papers, 2021 to 2022). "This group consists of two duos of mother and child, respectively, of Hungarian and Italo-Spanish origin, with LGMD-D2 myopathy phenotype, respectively, due to two different single nucleotide deletions in the TNPO3 gene." (PMID 33445560, 2021).
tumor (2 papers, 2021 to 2022). "Herein, we tried to uncover the interaction between tumour‐associated RBPs and circ‐TNPO3." (PMID 35876041, 2022). "We grouped the ccRCC sample cohort (n = 110) according to the WHO/ISUP stage, tumour T stage and distant metastasis to compare the circ‐TNPO3 levels among these groups." (PMID 35876041, 2022). "In our study, we proved that circ‐TNPO3, a novel tumour suppressor, was downregulated in ccRCC and suppressed the migration and proliferation of ccRCC cells." (PMID 35876041, 2022). "Further study showed that the tumor-promoting role of SRSF1 can be significantly attenuated by silencing TNPO3, confirming that only nucleus SRSF1 exerts pro-oncogenic effects." (PMID 33602301, 2021). "Here, we validated that circ‐TNPO3 could bind directly to IGF2BP2, belonging to the IGF2BPs family, which is associated with tumour development." (PMID 35876041, 2022). "Synergistically, IGF2BP2 may be involved in inhibiting tumour migration induced by circ‐TNPO3." (PMID 35876041, 2022). "The lower circ‐TNPO3 expression was found in ccRCC patients with distant metastasis, higher World Health Organization/International Society of Urologic Pathologists (WHO/ISUP) grade and more advanced tumour T stage." (PMID 35876041, 2022). "In summary, we verified the downregulation of circ‐TNPO3 in ccRCC and its negative correlation with distant metastasis, WHO/ISUP grade and tumour T stage." (PMID 35876041, 2022).
autosomal recessive disease (1 paper, 2019). Autosomal recessive form of disease. "LGMD1F is an autosomal recessive disease and accordingly, both TNPO3_wt and TNPO3_mut form are co-expressed in similar quantity." (PMID 31465518, 2019).